U2 (U2 spliceosomal RNA )
Synonyms: LOC124904142
Gene: Small nuclear RNA gene on chromosome 17 (43,284,139 to 43,284,329, reverse strand). Ensembl gene ENSG00000274062.
Gene Ontology:
Molecular function: pre-mRNA branch point binding
Biological process: mRNA branch site recognition
Cellular component: U2 snRNP
Homologues: Orthologues: chimpanzee U2 (100% identical), macaque U2 (100% identical), dog U2 (99% identical), pig U2 (48% identical), rat LOC120094029 (36% identical). Paralogues in human: U2 (100% identical), RNU2-2 (96% identical), U2 (95% identical), RNU2-3P (93% identical), RNU2-4P (93% identical), RNU2-17P (90% identical), RNU2-6P (90% identical), RNU2-48P (89% identical), RNU2-52P (89% identical), RNU2-59P (89% identical), RNU2-25P (87% identical), RNU2-26P (87% identical), and 68 more.